TERT (telomerase reverse transcriptase)
Diseases named in the same sentence as TERT in open-access papers (continued):
Sharing a sentence is not in itself a finding about the gene and the disease.
chondrosarcoma (10 papers, 2018 to 2025). A malignant cartilaginous matrix-producing mesenchymal neoplasm arising from the bone and soft tissue. "TERT mutations were also identified in approximately 35% of dedifferentiated chondrosarcomas in Nacev’s study." (PMID 38254737, 2024). "Genomic profiling has revealed telomerase reverse transcriptase (TERT) gene amplification and ATRX mutations, in addition to TERT promoter mutations, in approximately 20% of high-grade chondrosarcomas and DDCSs." (PMID 38275833, 2024). "Activating promoter mutations in telomerase reverse transcriptase (TERT) was recently described by us and others as a frequent mutation in high-grade chondrosarcoma." (PMID 34108637, 2021). "In this study, we investigate the prognostic significance of TERT promoter mutations in 241 chondrosarcomas from 190 patients collected over 24 years (1994–2017)." (PMID 34108637, 2021). "As an easily analyzed marker, there is future potential to utilize TERT promoter mutation status as a prognostic marker and investigate telomerase-targeted therapy in chondrosarcomas." (PMID 34108637, 2021). "Of note, 10 out of 11 (91%) mutations found were C228T and only in one patient with chondrosarcoma we observed a TERT promoter mutation at position C250T." (PMID 29463038, 2018). "Our data suggest that subclonal TERT promoter mutations may be a central event for tumor progression in chondrosarcoma, and its identification might be helpful to identify patients with higher risk of tumor metastasis." (PMID 34108637, 2021). "There was a significant association between TERT promoter mutation status and higher chondrosarcoma grade (p < 0.0001), as well as metastasis (p < 0.001), and both overall (p < 0.001) and disease-specific mortality (p < 0.001), but not with local recurrence (p = 0.390)." (PMID 34108637, 2021). "In clinical routine pathology, the identification of TERT promoter mutations may also help verify if the suspicious cell population is truly neoplastic, rather than tumor-associated reactive spindle cell areas frequently observed in chondrosarcomas." (PMID 34108637, 2021). "We identified oncogenic TERT amplifications in 44% (8/18) of intimal sarcoma (INTS) and TERT promoter mutations in 79% (38/48) of MRLS, 46% (24/52) of SFT, and 35% (5/14) of dedifferentiated chondrosarcoma (DDCHS)." (PMID 35705560, 2022). "The TERT promoter was sequenced after microdissection of 135 chondrosarcomas from 106 patients in addition to data from our previous cohort." (PMID 34108637, 2021). "In this study, we aimed to validate the prognostic value of TERT promoter sequencing by analyzing the vast majority of chondrosarcomas treated in our institution over a period of 27 years." (PMID 34108637, 2021). "Moreover, (epi)genetic alterations in the TERT gene (i.e., hypermethylation and promotor mutations) affect the survival probability of IDH1MUT chondrosarcoma patients, whilst this association is absent in IDHWT and IDH2MUT patients." (PMID 37509266, 2023).
Hypertension (10 papers, 2022 to 2026). The presence of chronic increased pressure in the systemic arterial system. "The G allele in the locus of rs2736100 TERT was associated with hypertension prevalence and was more prevalent in hypertensives patients (46.00% vs. 24.49%, p = 0.011)." (PMID 36359275, 2022). "Our data are consistent with the results of a human study, showing that patients with hypertension with lower blood TERT concentration had ineffective BP control and worse metabolic profiles in adipose tissues." (PMID 41368704, 2026). "The SNPs of the TERT gene (rs2736100 and rs2853669) were found to affect arterial hypertension prevalence." (PMID 36359275, 2022). "First, the patients were compared based on the rs2736100 SNP, in which significant differences between the TERT SNP and arterial hypertension diagnoses were observed." (PMID 36359275, 2022). "The absence of TERT rs2736100 T allele, male sex, and arterial hypertension are independent risk factors for phasic SB." (PMID 35159976, 2022). "The regression analysis showed that lack of TERT rs2736100 T allele, male gender, and arterial hypertension are the risk factors for the higher value of phasic BEI." (PMID 35159976, 2022). "The TERT A/C was seen in hypertension patients having significantly shorter LTL (0.98 ± 0.98 vs 1.76 ± 1.75, P = 0.003), which may result from defective TERT." (PMID 38192544, 2024).
liver cirrhosis (10 papers, 2010 to 2023). "Yet in order to utilize the detection of ctDNA TERT promoter mutations of patients with liver cirrhosis to detect HCC early, those results must be combined with magnetic resonance imaging (MRI) surveillance." (PMID 35159010, 2022). "Telomere shortening and reactivation of telomerase, through TERT promoter mutations, for example, represent genetic risk factors for the development of liver cirrhosis and liver cancer." (PMID 32722302, 2020). "Both HCC and PDAC develop through multiple stages, and these stages are associated with specific mutations e.g., KRAS as an early mutation that occurs in PanIN, and TERT promoter methylation that occurs following liver cirrhosis." (PMID 31608239, 2019). "Most of the TERT mutation carriers with pulmonary fibrosis, blood dyscrasias or liver cirrhosis were 40 years of age or older." (PMID 20502709, 2010). "Similarly, crytogenic liver cirrhosis is found in one TERT mutation carrier, but elevated liver function tests are seen in 11 individuals." (PMID 20502709, 2010). "The TERT C228T mutation was detected in the plasma of 42 of the 95 HCC patients (44%), not in the plasma of any patients with liver cirrhosis, and in tumor tissue of 68% of HCC biopsy samples." (PMID 35159010, 2022). "The authors analyzed TERT and TERC mutations in buccal mucosa tissue and peripheral blood of patients with liver cirrhosis and compared them with healthy non-cirrhotic controls." (PMID 32722302, 2020). "However, changes in the methylation level of the “driver” genes for oncopathology (АРС, CDKN2B, GSTP1, ELF4, TERT, WT1) are registered in tumor tissue in the setting of liver cirrhosis but not fibrosis." (PMID 36923478, 2023).
renal cell carcinoma (10 papers, 2014 to 2024). "Finally, the associations between TERC and TERT polymorphisms and clinical parameters of renal cell cancer had been further investigated." (PMID 29100352, 2017). "For example, reactivation of a systemic anti-TERT Th1 response after everolimus treatment improved patient survival in renal cell carcinoma by counterbalancing immune-suppressive Tregs." (PMID 31358938, 2019). "As urine-based tests are also applied for other urological malignancies including renal cell carcinoma (RCC), and upper tract urothelial carcinomas (UTUC), it is important to ascertain whether TERT promoter mutations are specific to BC only or widely present in different urological malignancies." (PMID 24742867, 2014).
conjunctival melanomas (9 papers, 2017 to 2023). "Other genes involved in the development of conjunctival melanoma are TERT promoter, NRAS and NF1 in which pathogenic mutations are described." (PMID 33396957, 2020). "TERT promoter mutations, which cause an increased TERT expression, are detectable in 32–41% of conjunctival melanomas and in 8% of PAM cases." (PMID 31683701, 2019). "An important element of distinction between conjunctival melanoma and uveal melanoma is given by the analysis of TERT promoter mutations: these mutations were present in about 30% of the former ones, but were absent in the latter ones." (PMID 29156643, 2017). "TERT promoter mutations were reported in conjunctival melanomas, ranging from 0 to 32% and, so far, only one case of uveal melanoma harbouring a TERT promoter mutation was reported." (PMID 28662141, 2017). "Furthermore, an increased telomerase activity with TERT promoter mutations can be found in about 40% of conjunctival melanomas." (PMID 31683701, 2019). "Telomerase reverse transcriptase (TERT) promoter mutation rarely causes uveal melanoma, representing about 1% of cases, while it is more common in conjunctival melanoma (41%) and primary-acquired melanosis (PAM) with atypia (8%)." (PMID 31109147, 2019). "Thus, reverse transcriptase inhibitors, such as azidothymidine (AZT), may become possible candidates for therapies directed against TERT-promoter mutant conjunctival melanomas." (PMID 31683701, 2019).
ependymoma (9 papers, 2014 to 2024). A WHO grade II, slow growing tumor of children and young adults, usually located intraventricularly. "Loss of chr6 (20/50 cases), as well as TERT mutations (21/50 cases), were frequent events enriched in tumors with pure ependymoma morphology (p < 0.001) and confined to areas with ependymoma differentiation in mixed tumors." (PMID 33755803, 2021). "In two mixed ependymoma–subependymoma samples (cases #33 and #36), spatial TERT sequencing revealed a C228T mutation in the ependymoma component and wild type sequences in the subependymoma component." (PMID 33755803, 2021). "A recent study evaluating the presence of TERT promoter mutations in ependymal tumors across different age groups demonstrated mutations in 9/120 samples (7%) occurring in conventional ependymomas diagnosed in adults." (PMID 33755803, 2021). "Clinically, pure ependymoma phenotype, chr6 loss, and TERT mutations were associated with shorter progression-free survival (each p < 0.001)." (PMID 33755803, 2021). "TERT promoter mutations were enriched in tumors with ependymoma phenotype: all 12/12 (100%) ependymomas showed a mutation as compared to 6/23 (26%) mixed ependymomas-subependymomas and 3/13 (23%) subependymomas (Chi-square, p = 3.4 × 10–5)." (PMID 33755803, 2021). "A TERT promoter mutation was observed in tumors Epe004 and Epe005 obtained from the same ependymoma patient." (PMID 28468611, 2017). "In PFSE tumors with pure ependymoma phenotype, TERT-mutation/Chr6-loss is associated with increased risk of recurrence and these alterations might therefore represent useful markers for more aggressive therapy regimes." (PMID 33755803, 2021). "Furthermore, we were able to demonstrate that TERT promoter mutations exclusively occurred in the ependymoma component in two mixed tumors (#33 and #36)." (PMID 33755803, 2021). "While dysregulated telomere biology has been implicated in ependymoma progression and prognosis, the TERT promoter mutations associated with telomerase reactivation are uncommon in both childhood and adult ependymomas, as are the ATRX mutations associated with ALT." (PMID 33115534, 2020). "In pediatric ependymoma, hypermethylation of the TERT promotor has consistently been associated with telomerase reactivation, indicating that epigenetic mechanisms of telomere maintenance may also enable replicative immortality in ependymoma cells." (PMID 33115534, 2020). "Ependymoma also has well-known amplified genomic regions, but only a gain of the TERT gene was identified by Johnson's group as well as by our methodology." (PMID 26185765, 2015). "TERT promoter mutation status most clearly segregated progressing and stable tumors and these high-risk PFSE tumors showed significantly worse outcome compared to a previously published series of 137 PFB ependymomas." (PMID 33755803, 2021). "Other proposed prognostic molecular markers of ependymomas include TERT and EZH2 expression." (PMID 30514397, 2018). "There are currently no specific antibodies for telomerase available and hTERT mRNA analysis has shown poor correlation between TERT mRNA expression levels and enzymatic activity, albeit this discordance has not been shown specifically in pediatric ependymoma." (PMID 25120190, 2014).
follicular adenomas (9 papers, 2019 to 2023). "In fact, out of the 552 cases of follicular adenomas studied in these different series, only one study reported a positive case for a TERT promoter mutation." (PMID 36672362, 2023). "Of the studies examining TERT promoter mutations in patients with follicular adenomas, the reported occurrence is ~0%." (PMID 36672362, 2023). "Although infrequent, others have detected TERT mutations in follicular adenomas." (PMID 32767735, 2020). "A 2018 study of follicular neoplasms found the upstream TERT promoter was methylated significantly higher in FTC (13%) than follicular adenoma (8%)." (PMID 32849278, 2020). "A 2018 study, limited to follicular tumors, found three or more copies of TERT in 6/77 (7.8%) of FTCs, 2/43 (4.7%) of follicular adenomas, and 4/19 (21%) of follicular tumors of uncertain malignant potential." (PMID 32849278, 2020). "Almost all previous studies reported no collective prevalence of TERT promoter mutations in normal thyroid parenchyma or benign thyroid lesions, such as nodular goiter (hyperplasia lesions), diffuse toxic goiters, lymphocytic (Hashimoto’s) thyroiditis, and follicular thyroid adenomas (FTA)." (PMID 31655978, 2020). "ACE2 was also decreased in follicular adenomas that were negative for TERT mRNA expression (p = 0.017)." (PMID 37568724, 2023).
malignant glioma (9 papers, 2013 to 2025). A grade III or grade IV glioma arising from the central nervous system. "The TERT promoter revertant mutation could inhibit proliferation of malignant glioma cells in vitro; however, at the same time, we hypothesized that the TERT revertant mutation can induce growth inhibition and apoptosis." (PMID 35053139, 2022). "Recently, a preclinical study packaged CjABE into AAV for the treatment of TERT-124 C>T malignant glioma." (PMID 35053139, 2022). "We further confirmed the nuclear staining of TERT by TMab-6 in U87 malignant glioma cell lines that were previously reported to possess TERT hotspot mutations as well as upregulated TERT transcripts." (PMID 29693015, 2018). "Further evidence for a regulatory link between EGFR and TERT was reported recently in malignant glioma, where 92% of cases harboring EGFR amplification were accompanied by a mutation in the TERT promoter." (PMID 24152305, 2013).
mucosal melanoma (9 papers, 2017 to 2025). A melanoma that arises from a mucosal site. "We identified mutually exclusive loss of function ATRX mutations and putatively activating TERT promoter mutations and amplifications, suggesting that both maintenance mechanisms are important in distinct subsets of mucosal melanoma." (PMID 31320640, 2019). "In mucosal melanoma, mutations in the SF3B1 gene impact those in the promoter of telomerase reverse transcriptase (TERT)." (PMID 40370819, 2025). "TERT methylation and expression have been reported to be closely related to the prognosis of patients with cancer, including mucosal melanoma, although its effects on immune infiltration have been shown to be cancer type specific." (PMID 38695555, 2024). "The combined inhibition of CDK4, MDM2 and TERT presents a promising therapeutic strategy for mucosal melanoma, as amplifications of these three genes frequently co-occur in this cancer subtype." (PMID 39598629, 2024). "All but one of the eight tumors in this study with translocations between 5p and 12p, usually resulting in amplifications of MDM2/CDK4 and TERT, were oral mucosal melanomas and of East Asian ancestry." (PMID 31320640, 2019). "TERT hypermethylation may contribute to the favorable responses observed in patients with mucosal melanoma undergoing immunotherapy." (PMID 38695555, 2024). "Our results indicated that PMME shows a distinct methylation landscape compared with NEMM, and the epigenetic status of TERT might be used to estimate prognosis and direct anti-PD-1 treatment for mucosal melanoma." (PMID 38695555, 2024). "Our results suggest that TERT methylation could potentially serve as a predictive biomarker for ICIs in mucosal melanoma." (PMID 38695555, 2024). "For example, in mucosal melanoma, there is a frequent occurrence of CDK4 protein expression in combination with TERT (telomerase reverse transcriptase) amplification." (PMID 39598629, 2024). "At present, some studies have found that mutations that activate SF3B1 and KIT, the deletion of CDKN2A, PTEN, or SPRED1, and the amplification of CDK4, TERT, KIT, MDM2, or CCND1 are common in mucosal melanoma." (PMID 38065883, 2023).
myeloma (9 papers, 2012 to 2025). "This study aimed to assess the clinicopathological impact of telomere length and telomerase reverse transcriptase (TERT) polymorphic variant, rs2242652, on multiple myeloma (MM) patients." (PMID 31814184, 2020). "The aim of the present study was to assess the relative telomere length and TERT gene polymorphism and their impact on survival and response to therapy in a cohort of Egyptian myeloma patients." (PMID 31814184, 2020). "We demonstrated that in multiple myeloma, both miRNA-143 and miRNA-138 expression and the level of TERT are increased." (PMID 39769169, 2024). "Interaction between TERT and NF-κb subunit p65 modulates TERT nuclear translocation in myeloma cells." (PMID 31179925, 2019). "The first evidence indicating that TERT regulates NF-κB-dependent gene expression was reported in multiple myeloma cells in which NF-κBp65 subunit was found to modulate the nuclear translocation of TERT." (PMID 31911897, 2019). "TERT may also form a part of a TERT–NF-κB subunit p65 complex, which can move from the cytoplasm to the nucleus in multiple myeloma cells, upon TNF‐α induction." (PMID 33329574, 2020). "TERT can also interact with oncogenic transcription factors such as NF-κB subunit p65 (RelA) and this interaction has been found to mediate translocation of TERT into the nucleus in multiple myeloma cells." (PMID 28264499, 2017).